IL6 (interleukin 6)
Diseases named in the same sentence as IL6 in open-access papers (continued):
Sharing a sentence is not in itself a finding about the gene and the disease.
epilepsy (continued). "An in vitro study suggested that after epilepsy, IL-1β mRNA, IL-6 mRNA, and TNF-α mRNA were expressed by microglia and astrocyte." (PMID 34976232, 2021). "Secondly, various inflammatory mediators such as CXCL9, CXCL3, and IL-6 have been shown to be dysregulated in patients with drug-resistant epilepsy." (PMID 34497517, 2021). "LPS-stimulated astrocytes can be present during inflammatory response (promote IL-1β, IL-6, and TNF-α expression) and be used to mimic epilepsy-inflammation to assess the underlying molecular or cellular mechanisms." (PMID 33776905, 2021). "With regards to IL-6, previous studies in epilepsy patients showed that IL-6 levels are higher acutely post-seizures, while the baseline level of IL-6 in chronic epilepsy are lower." (PMID 34572093, 2021). "Post hoc analysis with Tukey's test for multiple comparisons revealed increased IL-6 levels in the epilepsy group (AA, AV, and VV genotypes) when compared to their genotypes from the control group, respectively." (PMID 32219137, 2020). "And the longer the duration of seizure, the higher serum IL-6 levels was in our children with epilepsy." (PMID 32151248, 2020). "The most studied cytokines regarding astrogliosis and epilepsy are interleukin-1 beta (IL-1β), IL-6, and tumor necrosis factor-alpha (TNF-α); pro-inflammatory cytokines that can be released by reactive astrocytes and activated microglia." (PMID 33324329, 2020). "Pearson's analysis demonstrated an interesting correlation between IL-6 and caspase-3 (r = 0.5, p < 0.05) in the epilepsy group (VV genotype)." (PMID 32219137, 2020). "Of note, our results demonstrated increased IL-6 and caspase-3 levels in the epilepsy group when compared to the control group." (PMID 32219137, 2020). "In the clinic, in a small cohort study of patients with neonatal HI, elevated IL-6, TNFα, and IL-1β were found to be associated with the subsequent onset of epilepsy, suggesting that these cytokines may hold value as predictive biomarkers of later life epilepsy risk." (PMID 32116690, 2020). "It was reported that the levels of inflammatory cytokines including tumor necrosis factor alpha, interleukin-6, and interleukin-1 beta as well as interleukin-1 receptor antagonist significantly increased in patients with epilepsy." (PMID 32341973, 2019). "Collectively, TRPV1 promoted astrocyte migration thus helped the infiltration of pro-inflammatory cytokines (TNF, IL-1β, IL-6, and iNOS) from astrocytes into the vicinity of neurons to promote epilepsy." (PMID 31722723, 2019). "In our research, we found that the protein expression of pro-inflammatory factors, including TNF-α, IL-1β, IL-6, and IL-10, was higher in pilocarpine-induced epilepsy." (PMID 31231220, 2019). "In our model of virus-induced seizures/epilepsy, we found that IL-6 played a major role in acute seizures, and infiltrating macrophages were the major producers of IL-6." (PMID 31325960, 2019). "IL-1 and IL-6 are two of the most commonly approached proinflammatory cytokines in studies conducted to evaluate inflammation in drug-resistant epilepsy." (PMID 29401729, 2018). "Other authors report an increase of IL-6 concentrations in patients with epilepsy compared with those in control subjects." (PMID 29401729, 2018). "Elevated IL-6 level in serum or cerebrospinal fluid has been widely observed in patients as well as in animal models with different types of epilepsy." (PMID 29464573, 2018). "Pro-inflammatory cytokines, such as tumor-necrosis factor (TNFα) and interleukin-6 (IL-6), were increased in epilepsy patients and epilepsy models." (PMID 29566716, 2018). "Because many events including injury, response to injury, neuronal regeneration, and epileptogenesis are ongoing in the OHSC model, it is difficult to understand the effect of blocking the multifunctional properties of IL-6 on the development of epilepsy." (PMID 29464573, 2018).
epilepsy (continued). "Authors have suggested different theories like inflammation by Interleukin-6 (IL-6), autonomic dysregulations or altered ion channel due to drug resistant epilepsy." (PMID 29018647, 2017). "Our data demonstrate that the patients who developed cerebral vasospasm, delayed neurological deficits, chronic hydrocephalus, and symptomatic epilepsy showed elevated systemic IL-6 levels." (PMID 29194369, 2017). "Here, our findings support the existence of persistent inflammation in the ventricles of rats with epilepsy, which exhibited elevated levels of IL-6." (PMID 28649227, 2017). "IL1β & IL6 are found to have pro-epileptogenic properties in animal models for epilepsy, particularly, IL1β, which affects neuronal Ca2+ influx through NMDA dependent signalling." (PMID 29162878, 2017). "Isolated microglia from epilepsy tissue express IL-6 (1,614 ± 109 pg/mL), MCP-1 (11,223 ± 524 pg/mL) and IL-8 (25,455 ± 1,378 pg/mL) basally whilst IP-10 was absent (0 ± 0 pg/mL)." (PMID 26778406, 2016). "Levels of IL-6 mRNA were increased within the hippocampi of rats with epilepsy, and IL-6 was also involved during the process of kindling." (PMID 27882059, 2016). "For example, serum IL-1b, IL-1Ra, IL-2, IL-4, IL-6, IL-8, IFNγ, and IL-17 concentrations were observed to be elevated in patients with epilepsy." (PMID 26626560, 2015). "Multivariate regression analysis indicated that interictal concentrations of serum IL-6, IFNγ, IL-17a, IFNλ3, and CSF IL-6, IL-17a, IFNλ3 were significant biomarkers for patients with severe epilepsy." (PMID 26626560, 2015). "Among 14 cytokines, four independent biomarkers (IL-6, IFNγ, IL-17a and IFNλ3) for severe seizures in three different types of epilepsy were identified." (PMID 26626560, 2015). "Previous publications have indicated elevated IL-6 level after focal and generalized seizures in patients with epilepsy." (PMID 26626560, 2015). "Among all cytokine concentrations, only IL-6 level was correlated to all three severity scaling systems in all three types of epilepsy." (PMID 26626560, 2015). "If seizure frequency was used for seizure severity, then levels of IL-6, IL-8 and IL-17a were significant biomarkers in all three types of epilepsy." (PMID 26626560, 2015). "If VA score was applied, IL-1Ra, IL-6, IFNγ, IFNλ3 and IL-17a were severity markers in all types of epilepsy." (PMID 26626560, 2015). "IL-6 has also been suggested to be involved in the control of epilepsy, as well as neuronal damage and protection." (PMID 24348794, 2014). "For epilepsy and bipolar disorder, overlapping results regarding the cytokine system have been reported, namely, alterations of IL-1β, IL-2, IL-4, IL-6, and TNF-α." (PMID 24757498, 2014). "The higher plasma levels observed in this study of IL-6, IL-1β, IL-2, and IL-8, also support the concept that innate immunity is chronically activated in epilepsy." (PMID 23293627, 2012). "The median value for IL-6 in control plasmas is 1.1 ± 0.2 pg/mL, while in epilepsy plasmas the value is 3.1 ± 1.3 pg/mL." (PMID 23293627, 2012). "Previously, cytokines and chemokines had been found to be elevated in epilepsy patients, including high levels of IL-6 postictally." (PMID 23293627, 2012). "When IL-6 is analyzed as a composite ratio to sICAM5, the IL-6/sICAM5 ratio can discriminate between epilepsy and control plasmas by a factor of 14.9-fold." (PMID 23293627, 2012). "There was a significant correlation between a family history of epilepsy and specific cytokine levels: IL-6 and MCP-1 were higher in patients with family history of epilepsy than sporadic cases (p < 0.05)." (PMID 20021679, 2009). "In addition, it has been shown that VU0360172, a mGlu5 PAM, can reduce seizures in virus-induced epilepsy model mice and also reduce IL-6 and TNF-α production." (PMID 39858450, 2025).
epilepsy (continued). "Other Ct/Cm concentrations were significantly higher in MUE cases (IL‐8: median 101 pg/mL, range 144, p = 0.019; IL‐18: median 3 pg/mL, range 0.52, p < 0.001; MCP‐1: median 814 pg/mL, range 1319, p = 0.004; and IL‐6: median 5 pg/mL, range 16, p < 0.001) compared to epilepsy and neoplasia." (PMID 40859633, 2025). "This suggests that the IL-6 signaling transpathway may play a role in the pathway of comorbid depressive disorder in epilepsy." (PMID 39858450, 2025). "Prolonged expression of reactive microglia in KA-induced epilepsy contributes to the production of proinflammatory cytokines such as tumor necrosis factor alpha (TNF-α), interleukin-1β, and interleukin-6 resulting in neuronal loss and the promotion of epileptic seizures." (PMID 41233341, 2025). "For example, elevated levels of IL-6 and IL-1β have been found in epilepsy patients." (PMID 39091611, 2024). "A significant increase in proinflammatory cytokines, including IFN-γ, IL-1β, IL-6, IL-10, IL-12, and TNFα, was observed after epileptogenesis, and levels of these inflammatory factors may serve as biomarkers for epilepsy." (PMID 39249163, 2024). "Furthermore, some inflammatory mediators, such as TNF‐α, IL‐1β, and IL‐6, play a significant role in the development of epilepsy, and Crocin presents an inhibitory effect on these inflammatory cytokines." (PMID 38775292, 2024). "Intranasal administration of IL-6 could increase the severity of epilepsy induced by pentylenenetrazole." (PMID 38074156, 2023). "Based on the present results, ferroptosis-related hub genes NFE2L2, PTGS2, IL6, JUN, HMOX1, and TLR4 have good diagnostic value for epilepsy and may be potential early biological diagnostic targets." (PMID 37946105, 2023). "Moreover, we made subgroups of patients based on their types of epilepsy, etiologies, and abnormal MRI, and compared the IL-6 and IL-10 levels and their ratio, in different GADA groups." (PMID 37025699, 2023). "Therefore, in this study, we investigated the association of plasma cytokine concentrations of IL-6 and IL-10 and their ratio with GADA in patients with drug-resistant epilepsy." (PMID 37025699, 2023). "However, in a large retrospective study of 1218 patients with epilepsy, interictal IL-6 levels were positively correlated to seizure frequency and severity in both TLE, XTLE and idiopathic generalized epilepsy." (PMID 36895367, 2023). "Serum IL-6 levels are elevated significantly after stroke, and its chronic elevation and upregulation may contribute to the onset of epilepsy." (PMID 36338344, 2022). "IL-6 is predominantly secreted from glial cells and generates a favorable environment for the development of epilepsy by decreasing hippocampal neurogenesis and long-term potentiation (LTP), increasing gliosis and increasing the blood-brain barrier permeability." (PMID 36338344, 2022). "Furthermore, these authors also studied seven adult patients with epilepsy treated with VNS in whom a reduction of IL-6, IL-1β, and TNF blood production was observed." (PMID 36010024, 2022). "In the pathogenesis of epilepsy, IL-6 has demonstrated a dichotomous role." (PMID 35625063, 2022). "Previous studies demonstrated that different inflammatory mediators, including tumor necrosis factor (TNF)-α, IL-1β, and IL-6, may contribute to epilepsy development and progression." (PMID 35647304, 2022). "To date, modulation of neuroinflammation by the GM through uncontrolled activation of Th-17, production of IL-1-b, IL-6, and TNF-α, as well as a reduction of SCFAs that result in BBB alterations, are the only known causal interactions that determine the onset of epilepsy." (PMID 36138769, 2022). "Interestingly, exploring the clinical features of GBM patients, we found a significant change in IL6 expression between the two KDM5C subgroups with epilepsy." (PMID 36142158, 2022).
epilepsy (continued). "Proinflammatory cytokines (IL-1β, IL-6, and IL-18) contribute to the pathophysiology of epilepsy through several pathways: modulating glutamatergic transmission, enhancing N-methyl-D-aspartate receptor function by activation of SRC tyrosine kinase, and altering GABAergic neurotransmission." (PMID 35624482, 2022). "The determination of the IL-6 level is a good predictor of poststroke epilepsy." (PMID 33959658, 2021). "In addition, alterations in circulatory levels of proinflammatory cytokines such as interleukin-1β, tumor necrosis factor-α (TNF-α), IL-6, and interferon-γ have been reported in an animal model of epilepsy following DBS33." (PMID 34215817, 2021). "Exacerbated inflammation could be a consequence as well as a cause of epilepsy, and several inflammatory mediators, such as IL1β, TNF, and IL6, have been detected in surgically resected brain tissue from epileptic patients." (PMID 33407600, 2021). "Some reports have indicated that inflammation may extend beyond the CNS, and increased levels of proinflammatory cytokines such as IL-1β and IL-6 have also been observed in the blood of epilepsy patients." (PMID 33377994, 2021). "Furthermore, resident glial cells are rapidly activated and trigger the release of proinflammatory cytokines such as interleukin-1 (IL-1β), tumor necrotic factor-alpha (TNF-α), and interleukin-6 (IL-6), which clinically compromise the prognosis of epilepsy." (PMID 34422216, 2021). "The plasma concentrations of IL-1β and IL-6 may have potential utility as peripheral biomarkers of immune system activation in the course of epilepsy and translational potential for future clinical use." (PMID 33377994, 2021). "Finally, similar to KC/GRO levels, no changes were observed between conditions (control vs. status epilepticus/epilepsy) in plasma concentrations for IL-1β, IL-6, or IL-18 in wt mice." (PMID 34572093, 2021). "No changes could be observed in plasma levels between genotypes for IL-1β and IL-6 post-status epilepticus and during epilepsy." (PMID 34572093, 2021). "IL-1β, IL-6, caspase-1, and caspase-3 levels were increased in the epilepsy group (VV genotype)." (PMID 32219137, 2020). "Moreover, exosomal α-synuclein levels showed significant correlation with serum IL-6 levels in children with epilepsy and acquired demyelinating disorders of the CNS." (PMID 32151248, 2020). "Therefore, correlation between the serum IL-6 levels and exosomal α-synuclein supports the viscous neurotoxicity cycle of neuroinflammation in epilepsy patients." (PMID 32151248, 2020). "Furthermore, an important correlation between IL-1β vs. caspase-1 and IL-6 vs. caspase-3 was observed in the epilepsy group (VV genotype)." (PMID 32219137, 2020). "In fact, when the brain is affected by brain diseases (i.e., epilepsy), the microglia cells are activated, and this activation may lead to production of inflammatory cytokines as IL-β and IL-6." (PMID 32219137, 2020). "Prior studies demonstrate that elevated levels of interleukin-1β (IL-1β), interleukin-6 (IL-6), interleukin-8 (IL-8), and tumor necrosis factor (TNF) are linked to neuronal hyperexcitability and are found in serum and CSF of patients with epilepsy." (PMID 30344507, 2018). "However, although it is clear that IL-6 contributes to neural inflammation-induced epilepsy, more research is required for IL-6 to be considered in disease-modifying therapy." (PMID 29764485, 2018). "Investigation on post-surgery patients with intractable epilepsy revealed increased levels of HMGB1, TLR4, RAGE, NF-κB, p65 and inducible nitric oxide synthase (iNOS) in the brain of the epilepsy group as well as increased levels of IL-1, IL-6, TNF-α, TGF-β, and IL-10 in epilepsy patients." (PMID 30271319, 2018). "Specifically, IL-6 and IL6R are closely associated with neurological excitability; thus, it has been proposed that this pathway may be involved in epilepsy." (PMID 29958461, 2018).
epilepsy (continued). "Considering the high cooccurrence of epilepsy and T1D, it is possible that the commensal microbiota drive autoimmune epileptogenesis through expansion of Th17 cells mediated by spontaneous secretion of proinflammatory cytokines, for instance, IL-6 and IL-1β." (PMID 27882059, 2016). "On the other hand, IL-6 levels were higher in patients without epilepsy (z = 2.30, p = 0.021), underlined by an interictal epileptiform activity focused in the frontal brain region." (PMID 27983615, 2016). "If NHS3 was used, IL-6, IFNγ and IFNλ3 were good markers in all types of epilepsy." (PMID 26626560, 2015). "Although the role of miR-142 in IL-6 regulation under epileptic conditions is not clear, it might be consistent with a role of this miRNA and IL-6 in epilepsy as well as neuroinflammation in general." (PMID 25078263, 2015). "Interictal serum IL-6, IFNγ, IL-17a, IFNλ3, and CSF IL-6, IL-17a, IFNλ3 could be used as potential biomarkers for severe epilepsy." (PMID 26626560, 2015). "mRNA levels of IL-6, IFNγ, IL-17a, and IFNλ3 were elevated in different types of epilepsy." (PMID 26626560, 2015). "Compared with the levels in the two control groups (1.57±0.69 for the blank control group and 1.80±0.54 for the surgical control group), the IL-6 mRNA levels (mean 2.83±0.40) in the hippocampi of rats in the epilepsy group were significantly increased (P<0.05)." (PMID 24348794, 2014). "Therefore, the present study used the electrical kindling rat model of epilepsy to explore the possible roles of IL-6 and antiepileptic drugs in the incidence and treatment of epilepsy." (PMID 24348794, 2014). "The role of cytokines, including the IL6 system has been extensively studied in epilepsy." (PMID 24146813, 2013). "IL-6, IL-8, and TARC were included in this analysis because of their high baseline concentrations, statistical trend toward higher values in epilepsy patient plasma, and in the case of IL-6, solid literature showing altered plasma concentration in the epilepsy population." (PMID 23293627, 2012). "In a variety of animal models of epilepsy, as well as in patients suffering from epilepsy, increased elevations of pro-inflammatory cytokines IL-6, IL-1β and TNF-α have also been found in the cerebrospinal fluid, and many of these cytokines have been shown to have proconvulsant activity." (PMID 20067608, 2010). "However, valproates increase IL-1, IL-6, and IL-5 levels in patients with epilepsy." (PMID 40217882, 2025). "However, the IL-1β and IL-6 transcript levels were still significantly elevated (222.8 ± 35.2% and 117.1 ± 2.1% of those in the respective controls) at 7 weeks post-SE during the chronic phase of epilepsy." (PMID 41445743, 2025). "C-reactive protein (CRP) and interleukin-6 (IL-6) levels, which are indicators of oxidative stress and inflammation, play an important role in the evaluation of the effects on cardiac health as a result of carbamazepine administration in male rats used as epilepsy models." (PMID 41295638, 2025). "Other studies showed that in epilepsy models, Il6 upregulation could aggravate neuronal damage." (PMID 37047481, 2023). "However, this concept cannot be expanded to all epilepsies; using a rat model of audiogenic seizures, de Deus and colleagues reported similar levels of IL-6, IL-10, TNF-α and IL-1β between controls and experimental animals, but high correlation between seizure severity and nitrate levels." (PMID 35052661, 2022). "Pearson's analysis demonstrated in the epilepsy group which presented generalized seizures (VV genotype), an interesting correlation between inflammatory and apoptotic parameters: IL-1β vs. caspase-1 (r = 0.7, p < 0.05) and IL-6 vs. caspase-3 (r = 0.6, p < 0.05)." (PMID 32219137, 2020). "Interestingly, the proinflammatory cytokines IFN-γ, IL-1β and IL-6 were negatively correlated with the age of disease onset in children with epilepsy, suggesting that younger patients demonstrated a more aggravated inflammatory response to recent seizure attacks." (PMID 32151248, 2020).